CD4 (CD4 molecule)
Diseases named in the same sentence as CD4 in open-access papers (continued):
Sharing a sentence is not in itself a finding about the gene and the disease.
lymphopenia (continued). "In addition, coinfections also result in severe lymphocytopenia in the peripheral blood, reducing antibody levels and CD4+ T cell responses." (PMID 40333344, 2025). "Comprehensive immunological workup showed panhypogammaglobulinemia (IgG 262 mg/dL, IgM 42 mg/dL, IgA 7 mg/dL), lymphopenia (1170 cells/μL), reduced absolute B cells (20 cells/μL, 1.4% of lymphocytes), and decreased percentages of naïve CD4 T cells (10% of CD3+CD4+)." (PMID 41009791, 2025). "Similarly, RIPK1D138N mutation restored numbers of naive CD4+ and naive CD8+ T cells in Tnfaip3.Ikk2ΔTCD4 mice to near normal levels, confirming the dominant role of extrinsic cell death processes in the lymphopenia of Tnfaip3.Ikk2ΔTCD4 mice." (PMID 39327505, 2025). "Its development may be strongly associated with the use of monoclonal antibodies and high-dose corticosteroids, which delay immune reconstitution and lead to persistent CD4+ lymphopenia and immune dysregulation." (PMID 41179870, 2025). "The benefit of any additional prophylaxis for patients with CD4 lymphopenia remains unclear and additional studies are needed to inform management of these highly immunosuppressed patients." (PMID 39224237, 2024). "The patients’ CD4+ T cell lymphopenia, possibly coupled with reduced resident memory CD4+ T cells, may explain these infections." (PMID 39352394, 2024). "The immunological phenotype in APDS is characterized by a diminished antibody response to polysaccharide antigen, elevated IgM, normal IgG and IgA, B-cell lymphopenia, increased transitional B cells, reduced memory B cells, and CD4 lymphopenia, especially naïve CD4+ T cells." (PMID 38933494, 2024). "P3 developed lymphopenia during his third decade of life, with a count of total lymphocytes of 924 ± 266 cells/mmc (media ± SD), CD4 + T cells of 339 ± 94 cells/mmc (media ± SD), CD8 + T cells of 205 ± 59 cells/mmc (media ± SD), and NK cells deficiency of17 ± 7 cells/mmc (media ± SD)." (PMID 38578354, 2024). "Consistent with this hypothesis is the observation that effector memory P440S CD4+ T cells expanded and/or accumulated in the intestinal draining mesLN, despite the lymphopenia observed in other peripheral lymphoid organs." (PMID 37962568, 2024). "The increased ROS induced apoptosis, including CD4 lymphocytopenia." (PMID 39224595, 2024). "Research has focused predominantly on CD4+ T cells, resulting in an enhanced understanding of their phenotype in septic subjects, characterized by an initial lymphopenia followed by alterations in subtype frequency, decreased cellular diversity, and changes in effector function." (PMID 39691721, 2024). "Interestingly, TNF-α-mediated apoptosis of CD4+ T cells has also recently been shown to contribute to SARS-Co-V2-induced lymphopenia." (PMID 38256231, 2024). "Additionally, chronic leishmaniasis infections result in CD4 lymphopenia and a reduced CD4/CD8 ratio." (PMID 39407816, 2024). "Within T cells, CD4 lymphopenia was more pronounced than that of CD8 lymphopenia." (PMID 39270020, 2024). "ALZ has its most pronounced impact on cell immunity, leading to profound and extended lymphopenia, primarily affecting CD4+ lymphocytes, although the deficiency is never entirely exclusive." (PMID 39274345, 2024). "Our study was not designed to investigate factors associated with incident TB during ART, such as lack of viral suppression and persistent CD4 lymphopenia, that have been identified as risk factors for ART-associated TB in previous studies." (PMID 39193669, 2024). "Typically, MHC-II deficiency is characterized by hypogammaglobulinemia, CD4 lymphopenia and absent HLA-II expression on B cells and monocytes." (PMID 39072316, 2024). "Phenotypic and functional changes of the immune system, such as lymphopenia and T lymphocyte subset alterations, including reduced levels of CD4+ and CD8+ T cells, as well as a reduced CD4+/CD8+ ratio, have been described in patients with chronic kidney disease." (PMID 39274306, 2024).
lymphopenia (continued). "Drop of CD4 cells and a corresponding increase of HIV viral load were both observed before in clinical studies with regard to syphilis infection and a study on 84 PLWH that was published in 2018 showed a relative non-CD4 specific lymphopenia induced by syphilis infection." (PMID 37423969, 2024). "Lymphopenia, neutropenia, and CD4 T cells are essential factors in immunocompromised patients." (PMID 38030860, 2024). "Similarly, cryptococcosis remains as one of the most prevalent infection in patients with idiopathic CD4+ T cell lymphopenia." (PMID 39352394, 2024). "Such sepsis-induced lymphopenia has profound consequences on how T cells respond to infection but equally on the humoral immune response that is both elicited by B cells and supported by distinct CD4+ T follicular helper (TFH) cell subsets." (PMID 38197178, 2024). "As PWH may have an increased risk of developing CMV reactivation, including auto-HSCT recipients due to prolonged CD4+ lymphopenia prophylactic strategies specific to this population remain understudied." (PMID 39459894, 2024). "Severe CD4 T and B lymphopenia was observed below 100 and 20 cells/μL, respectively." (PMID 38540179, 2024). "Such sepsis-induced lymphopenia has profound consequences on how T cells respond to infection but equally on the humoral immune response that is both elicited by B cells and supported by CD4+ T follicular helper (TFH) cells." (PMID 38197178, 2024). "Lymphopenia due to low CD4+ added to by a subsequent fall of CD8+ may be the late immunological factor involved in relapses." (PMID 38921748, 2024). "Extensive lymphopenia (involving CD4+ AC) is potentially modulated by lymphocyte sequestering within tissues or proinflammatory cytokine-induced apoptosis and may contribute to defective viral clearance." (PMID 39224704, 2024). "Rarely solid and hematological malignancies and features of bone marrow dysfunction like anemia, lymphocytopenia, CD4 lymphopenia, neutropenia and eosinopenia may also be observed in patients with GS." (PMID 39246613, 2024). "Interestingly, idiopathic CD4 lymphocytopenia and HIV-induced immunodeficiency are associated with psoriasis, which implicates lymphopenia as a trigger of autoimmune dermatitis." (PMID 38576231, 2024). "Therefore, this study supports the theory, that at least initially, a profound CD4 + and BC lymphopenia is important for patients to achieve a sustained response after aHSCT." (PMID 38509633, 2024). "Shift towards exhausted and immunosenescent lymphocyte phenotype, CD4+ T-cell lymphopenia, reduced CD4+/CD8+ ratio, increased terminally differentiated T-cells, and chronic systemic inflammation are all described to be associated with uremia and progressive CKD." (PMID 39660122, 2024). "LAT deficiency is also associated with abnormal lymphocyte frequency and function, including progressive lymphopenia, reduced CD4+ and CD8+ T cell numbers, expansion of CD4-CD8- double negative T cells, and reduced activation and proliferation of T cells following anti-CD3/anti-CD28 stimulation." (PMID 39076976, 2024). "In addition, disseminated NTM infection is occur in the patients with idiopathic CD4 lymphocytopenia, which absolute CD4 T lymphocyte count of less than 300 cells/μL." (PMID 36717786, 2023). "Previous studies have described long-lasting CD4+ T lymphopenia after cytotoxic anticancer therapy." (PMID 37685612, 2023). "lymphopenia may refect a lower number of CD4 + T helper lymphocytes, resulting in a poorer lymphocyte-mediated immune response to malignancies." (PMID 36070068, 2023). "The increased apoptosis of CD4+ T lymphocytes in peripheral blood is related to lymphopenia." (PMID 38004652, 2023). "Moreover, these patients also manifested severe lymphopenia, as the counts of total lymphocytes, CD4+ T cells, and CD8+ T cells were extremely low compared to those in the recovered group." (PMID 37773701, 2023).
lymphopenia (continued). "Recently, this gene was involved in CD4 anergy and CD4 lymphopenia in HIV-infected patients." (PMID 37457832, 2023). "Ten cases showed lymphopenia with high rates of CD4+ < 200/μL." (PMID 36675909, 2023). "Additionally, prolonged CD4+ T cell lymphopenia has been reported in renal transplant patients that can persist for up to 10 years post-transplant, leaving individuals at an elevated risk of HPV disease persistence and allograft rejection." (PMID 36960048, 2023). "Moreover, TMS patients in relapse displayed a selective CD4 T-cell lymphopenia of cells with a Th2-like polarised phenotype." (PMID 36761741, 2023). "Due to the risk of herpes infections, antiviral prophylactic treatment with acyclovir 200–400 mg twice daily is recommended during the course of alemtuzumab until recovery of CD4 lymphocytes to >200 cells/μl, with a minimum treatment duration of 2 months even if CD4 lymphopenia resolves earlier." (PMID 36314777, 2023). "Here, we demonstrated that infected CD4+ T cells undergo cell death, which may contribute to the development of lymphocytopenia." (PMID 37523305, 2023). "A lymphocytopenia and impaired CD4+ T cell response can affect antiviral protection." (PMID 38146366, 2023). "The HEL : TCR dTg model of EAU is a CD4+ T cell mediated disease which develops spontaneously on photoreceptor maturation (~P20/21), and is driven by dysregulation in Teff/Treg cell balance occasioned by profound neonatal lymphopenia." (PMID 37727784, 2023). "Immunologically, all but ZAP70 present with early onset progressive CD4 lymphopenia." (PMID 38112969, 2023). "The peripheral blood monocyte count and L:M are not strong prognostic indicators in HIV-DLBCL, and while a low lymphocyte count is associated with poorer survival, this is a product of low CD4 counts, and not lymphopenia per se." (PMID 36630466, 2023). "However, the PB lymphopenia seems not only be attributed to a decrease of CD4+ T-lymphocytes, but also a decrease of CD8+ and CD19+ lymphocytes, the latter representing B-cells." (PMID 37161980, 2023). "An early study reported that patients with DM could develop lymphopenia, characterized by low peripheral CD4+ and CD8+ T‐cell and B‐cell absolute counts before initial treatment and a significant increase in lymphocyte counts after treatment." (PMID 37382274, 2023). "In the global cohort, a high IPI, advanced disease stage, 2/more extranodal sites, the PS, a low CD4 count, virological suppression, lymphopenia, neutrophilia, a high N:L, a high Treg count, high Treg expression of CD39 and a low MO-Y were all associated with survival on univariate analysis." (PMID 36630466, 2023). "Taken together, it is tempting to speculate that CiaHD could reverse some aspects of aberrant immunity in MHD, namely, CD4+ T-cell activation and lymphopenia." (PMID 37809041, 2023). "However, the pathogenesis of CD4+ T cell lymphopenia still lacks in-depth research, and further studies are needed to investigate the mechanisms of lymphopenia during severe M. tuberculosis infection and the possible treatment implications for these patients." (PMID 38004652, 2023). "Moreover, lymphopenia with low CD4+ cell count represented a consistent finding in patients diagnosed with PJP or IPA." (PMID 36675909, 2023). "Similarly, patients with poorly controlled Human Immunodeficiency Virus infection and CD4+ T cell lymphopenia have high rates of S. aureus infections, although it is not clear that this is specifically due to impaired T cell immunity." (PMID 36693884, 2023). "However, in this study, the adult protected cattle developed a delayed monocytosis, neutropenia and CD4+ lymphopenia in peripheral blood compared to the previous observation in young animals." (PMID 37583702, 2023). "Lymphopenia was mostly due to reduction in CD4+ T, B and central memory CD8+ T cells." (PMID 36675231, 2023).
lymphopenia (continued). "Indeed, CD4 T lymphopenia was found significantly more frequently in older patients including in patients with localized disease (mean age around 70 years)." (PMID 35546670, 2022). "Similarly, proliferative responses of CD4+ T cells were decreased in moderate patients with lymphopenia (p=0.05)." (PMID 36110850, 2022). "T CD4+ lymphopenia found in Case 3 could be another immunological factor resulting in refractory giardiasis." (PMID 36498582, 2022). "Thus, the use of CD4 lymphopenia in NSCLC as predictive biomarker deserves future confirmation even more during immunotherapy." (PMID 35546670, 2022). "SARS-CoV-2 infection can activate innate and adaptive immune responses and result in exacerbated inflammatory responses, including eosinopenia and lymphopenia, with severe reduction in the frequency of CD4+ and CD8+ T cells, B cells and natural killer (NK) cells." (PMID 36363816, 2022). "Multivariate analysis confirmed the worse prognosis associated with CD4+ T lymphopenia in local/loco-regional NSCLC, but not in metastatic patients (HR 2.028 [95% CI = 1.065–3.817] p = 0.02)." (PMID 35546670, 2022). "CD4 lymphopenia was reported with variable severity of COVID-19 infection." (PMID 35329872, 2022). "ESRD patients were characterized by severe lymphopenia [1500(1300-1800) vs 2250(1625-2250)cells/μl, P < 0.001] as well as decrease of all ‘immature’ and less-differentiated T cell subsets, predominantly affecting the CD4 compartment." (PMID 35615367, 2022). "They found that the exposure to a tumor vaccine during homeostatic recovery after induction of lymphopenia resulted in strong expansion of CD4+ and CD8+ CD44high CD62Llow effector memory T cells, accompanied by a pronounced tumor-specific IFN-γ production and better tumor reactivity." (PMID 35455309, 2022). "Furthermore, IL-7 has been shown to regulate CD4 T cell proliferation in conditions of lymphopenia indirectly though DCs22." (PMID 34997007, 2022). "Therefore, in the present study, we analyzed the prognostic value on overall survival of CD4+ T lymphopenia in patients with stage I to IV NSCLC." (PMID 35546670, 2022). "Consequently, GS patients often display an inverse CD4+/CD8+ ratio, CD4+ T cell lymphopenia, and impaired T cell mitogenic response." (PMID 36059463, 2022). "Also, an interesting result of our study was the CD4+ T cell lymphopenia observed at day 7 after Att-S74-T3Bo infection." (PMID 36466866, 2022). "UMAP 1 group which showed the most important changes, was characterized by rise of CD8 senescent and anergic subsets, despite the significant lymphopenia, which could be exclusively attributed to the significant reduction of naïve CD4 cells." (PMID 35615367, 2022). "Therefore, FDA-approved product label recommends prophylaxis with acyclovir from the start of treatment until CD4 + lymphocytes recover to at least 200 cells/μl, with a minimum duration of prophylaxis of 2 months even if CD4 + lymphopenia resolves earlies." (PMID 35378683, 2022). "Indeed, patients with severe COVID-19 present lymphopenia and low CD4+ and CD8+ T cells counts, as well as high percentages of programmed cell death-1 (PD-1) expression on T cells." (PMID 36605446, 2022). "Previous studies also reported that in the early stage of sepsis, enhanced apoptosis of CD4+ T lymphocytes and B lymphocytes occurred, and the absolute counts of peripheral blood lymphocytes decreased sharply, with persistent lymphopenia directly related to increased mortality in septic patients." (PMID 36567402, 2022). "In this study, we report what we believe are novel findings that the GDBSs, PCS and IS, impair mitochondrial fitness of CD4+ T cells and may thereby contribute to the CD4+ T cell lymphopenia characteristic of INRs." (PMID 35316209, 2022). "The patient displayed mild CD4+ T lymphopenia, with a normal percentage of naïve CD4+ T cells." (PMID 35338423, 2022).
lymphopenia (continued). "Consequently, neutrophilia and/or lymphopenia are correlated with the reduction of CD4+ T helper cells and cytotoxic CD8+ T cells in the tumoral stroma." (PMID 35958590, 2022). "Homozygous and hypomorphic missense mutations in CORO1A may present as early-onset EBV+B-LP as a result of CD4+CD45RA+ T-cell lymphopenia and impaired invariant NKT-cell development and survival defects." (PMID 35603189, 2022). "Importantly, MSN has also been implicated in the IL-15–dependent proliferation of CD8+ and CD4+ Tregs, while MSN deficiency results in lymphocyte egress from lymphoid organs, causing persistent lymphopenia in peripheral blood." (PMID 36119109, 2022). "We found that only peripheral CD4 lymphopenia influences the prognosis of NSCLC patients." (PMID 35546670, 2022). "However, patients with lymphopenia also had diminished CD4+ T cell proliferative responses under PHA stimulation (p=0.04)." (PMID 36110850, 2022). "While local CD4+ T-cell accumulation, proliferation, and activation are invariably observed within affected tissues, 10-50% of those with sarcoidosis paradoxically exhibit peripheral lymphopenia coupled with anergy or exhaustion." (PMID 36311769, 2022). "This induces more profound and long-term immunosuppression in these patients; for example, alkylate drugs, such as bendamustine, generate a prolonged CD4 lymphopenia which decreases up to 6 months after receiving the last dose and does not recover until 7–9 months after the end of treatment." (PMID 36428631, 2022). "Severe eosinopenia at admission was associated with a higher neutrophil-to-lymphocyte ratio (NLR) (7.66 vs. 6.07; p < 0.001), a lower lymphocyte count (p < 0.001) with a CD4+ lymphopenia (486/mm3 vs. 682/mm3; p = 0.001), and a higher platelet count (p < 0.001)." (PMID 36557676, 2022). "It should be noted that lymphopenia might occur due to consequent apoptosis of activated CD4+T cells by SARS-CoV-2, thereby inducing immune suppression." (PMID 36147602, 2022). "Moreover, SARS-CoV-2 and IAV coinfection is accompanied by severe lymphopenia which leads to reduced antibody and CD4+T cell responses against each virus." (PMID 35107382, 2022). "Consistent with this, we have recently identified increased frequencies of cytotoxic Granzyme B-expressing (GzB+) CD8+ T cells in TB-IRIS patients that arguably could be a compensatory mechanism in the face of severe CD4+ lymphopenia." (PMID 35432354, 2022). "Indeed, patients with SARS-CoV-2, especially those with severe pneumonia, have a dysregulated immune response at hospitalization and often develop immune suppression characterized by lymphopenia, mainly in CD4 and CD8 T cells after the pro-inflammatory phase." (PMID 34576791, 2021). "Consistent with other reports, lymphopenia was observed in the COVID patients, but this did not translate into differential loss of specific CD4+ or CD8+ T cell subsets." (PMID 34529726, 2021). "Further, within the time frame of 8–12 weeks, no lymphopenia was observed in Cracr2afl/flCd4-Cre mice, unlike the patient in this study, who shows progressive loss of CD4+ T cells." (PMID 34908525, 2021). "Lymphocytopenia in CD4+ is clearly related to poor prognosis in STEMI25." (PMID 34075154, 2021). "This resulted in peripheral CD4+ T cell lymphopenia, with significant reduction in the frequency and absolute count of CD4+ naïve T cells and increased frequency of activated CD4+ T cells in secondary lymphoid organs (spleen and lymph nodes), as compared to WT CD4+ SP cells (SP4) cells." (PMID 34211466, 2021). "The blood count was also normal except for deep lymphopenia with a CD4 count of 167/mm3." (PMID 34359324, 2021). "However, a few studies found that advanced liver disease during chronic HCV infection and HCV/HIV co-infection have been associated with slow regression of liver cirrhosis and persistent CD4+ lymphopenia despite SVR response." (PMID 35062255, 2021).